IL6 (interleukin 6)
Diseases named in the same sentence as IL6 in open-access papers (continued):
Sharing a sentence is not in itself a finding about the gene and the disease.
colitis (continued). "Mounting evidences highlight the strong association among IL-6, bacteria and colitis." (PMID 36389768, 2022). "Moreover, in the context of colitis-associated colon cancer, IL-6 is known to shift macrophage polarization towards tumor-promoting M2 macrophages." (PMID 36428508, 2022). "Decreasing levels of IL-6 and IL-1β have also been associated with the treatment of colitis." (PMID 33748287, 2021). "In a TPH1 knock out (TPH1(−/−)) colitis mice model, that lack 5-HT produced by ECs, it was found that macrophage infiltration, IL-1β, IL-6, and TNFα production and colitis-associated colonic tissue damage were significantly reduced compared to the control (TPH1(+/+)) mice." (PMID 33807994, 2021). "Additionally, chemerin aggravated the severity of colitis by causing extensive damage to the intestinal mucosa and increased pro-inflammatory cytokine levels in colon cells, including IL-6, TNF, and IFN-γ." (PMID 34640632, 2021). "In mice fed on PD, RS exposure for 14 days markedly worsened colitis symptoms afterward, as shown by colonic shortening, histology, loss of goblet cells, and inflammatory cytokines (IL-6, MCP-1, TNF-α)." (PMID 33431867, 2021). "The “clinical” progression of colitis was also confirmed by quantifying neutrophil infiltration in the lamina propria, according to the Nancy histological score, by measuring weight loss, serum IL-6, CRP, and Lipopolysaccharide (LPS)." (PMID 33431850, 2021). "Thus, the acetate and n-butyrate-mediated reduction of inflammatory cytokines, such as IL-6 and IL-8, seems to be another mechanism underlying the reduction of colitis." (PMID 33503995, 2021). "In contrast to acute and chronic DSS colitis, T cell-associated transcription factors or inflammatory cytokines were not altered, but we detected slightly increased mRNA levels of Il6, CD80, and Cd86 in PTPN2fl/flxCD11cCrexRAG−/− mice after naïve T cell transfer." (PMID 34201918, 2021). "Moreover, PDCD4 deficiency in mouse models aggravates colitis and colitis-associated CRC by promoting the IL-6/STAT3 pathway." (PMID 34771727, 2021). "Furthermore, the therapeutic efficacy of Eat2 was associated with decreases in IL-1α and IL-6 levels detected in colonic homogenates from mice with TNBS colitis." (PMID 32332834, 2020). "Also, TNF-α and IL-6 contribute immensely to loss of body weight in colitis by releasing neuropeptides that suppress appetite and precipitate cachexia." (PMID 32090060, 2020). "A recent study showed that mice deficient in ApoA-I exhibit exaggerated colitis, while administration of an ApoA-I mimetic peptide attenuated gut inflammation, which was associated with decreased secretion of IL-6 by epithelial enterocytes in response to LPS, abundant in the gut lumen." (PMID 31374929, 2019). "In addition, key cytokines associated with colitis (IL-1β, IL-6, and IL-17A) were significantly suppressed, following treatment with M2b macrophage exosomes." (PMID 31749791, 2019). "Further, deficiency of IL-17R (receptor) prevents the development of TNBS-induced murine colitis, including improving body weight loss, decreasing productions of IL-6 and local macrophage inflammatory protein-2, ameliorating colonic inflammation, and reducing tissue myeloperoxidase activity." (PMID 31886308, 2019). "In the TNBS-induced rat colitis model, the expression of hepcidin in the colon could be increased associated with the activation of IL-6/STAT 3 pathway." (PMID 31387229, 2019). "In conclusion, silibinin could protect against colitis-associated tumorigenesis in mice via inhibiting IL-6/STAT3, which showed promising chemopreventive potential of CAC." (PMID 30498394, 2018). "The induction and severity degree of colitis was assessed by evaluating the following end-points: body weight loss, clinical score, histological score, large intestine length, and inflammatory cytokine expression (IL-6, IL-1beta)." (PMID 30619271, 2018).
colitis (continued). "In line with this evidence, increased inflammation and IEC death in a three times DSS-mediated colitis of IL-6-deficient mice is a result of impaired IL-6-mediated signal transducer and activator of transcription 3 (Stat3) action providing survival capacities in normal and premalignant IECs25." (PMID 29695802, 2018). "Finally, the reported observation that Fondanol activates 15-LOX is interesting since, when overexpressed, this enzyme suppresses colitis-associated colon cancer through inhibition of the IL-6/STAT3 signaling pathway." (PMID 29710854, 2018). "In addition, a link between TGF-β signaling and IL-6/STAT3 signaling in the tumorigenesis of colitis-associated CRC has been demonstrated." (PMID 28852270, 2017). "In addition, ApoA-I inhibited STAT3, which plays a major role in suppressing LPS-induced production of the inflammatory cytokine IL-6, in a mouse model of colitis-associated carcinogenesis." (PMID 29245934, 2017). "Importantly, colitis-associated tumors developed in Sdc1-defficient mice were characterized by increased local production of IL-6, activation of STAT3, as well as induction of several STAT3 target genes that act as important effectors of colonic tumorigenesis." (PMID 28350804, 2017). "Since SAMe and MTA inhibited IL-6/STAT3 signaling in the colitis-associated colon cancer model and this pathway was shown to be critical for cancer invasion and metastasis, we examined whether SAMe and MTA might inhibit cancer cell migration." (PMID 29108270, 2017). "IL-6 could also be an inflammatory mediator responsible for causing/maintaining the colitis that was observed in the animals subjected to TNBS administration." (PMID 27576902, 2016). "STAT3 activation induced by IL-6 via JAK has been implicated in colitis-associated colon cancer." (PMID 27589954, 2016). "Moreover an increased expression of IL6 has been associated with an unfavorable prognosis in patients with various types of cancer including sporadic and colitis-associated CRC." (PMID 26109431, 2015). "Alternatively, if the double-deficient mice are as susceptible to DSS-induced colitis as Il-6−/−/Il-6r+/+ mice, this would suggest that IL-6 has another unknown receptor, which mediates the detrimental IL-6 signal in colitis, while IL-6R plays no role." (PMID 24993179, 2014). "Our findings showed an elevation of NF-κB/IL-6 expression that occurs over the examined time-points (after induction for 14–22 weeks) in association with the rapid increased macroscopic tumor number and dysplastic lesion degree in colitis mice." (PMID 25093140, 2014). "This could also be observed in our cellular model of H2O2-associated colitis for Il-13 and TGFβ, whereas levels of Il-6 and Il-8 remained unchanged." (PMID 23742011, 2013). "In addition, the HF-FO diet reduced both colitis-associated disease severity and colonic mRNA expression of the Th17 cell master transcription factor (RORγτ) and critical cytokines (IL-6, IL-17A, IL-17F, IL-21, IL-23 and IFNγ) versus HF (P<0.05)." (PMID 23166761, 2012). "Finally, the pro-inflammatory cytokines TNF-α, IFN-γ, IL-1β and IL-6, and anti-inflammatory cytokine IL-10 have been implicated in experimental and human colitis." (PMID 22844504, 2012). "Finally, Gerlach and colleagues demonstrate a critical role for the transcription factor NFATc2 in IL-6 signaling and colitis-associated CRC." (PMID 23109839, 2012). "IL6 signaling is mediated by STAT3 that is also associated with colitis disease development." (PMID 20423518, 2010). "Thus, systemic administration of an IKKβ-specific inhibitor reduced Stat3 activation and IL6-target gene expression and ameliorated disease in colitis-prone IL10-deficient mice." (PMID 20478049, 2010). "IL-6−/−-mice are reported to be less susceptible to DSS colitis." (PMID 18545662, 2008).
colitis (continued). "plantarum Q7 (LpQ7-MVs) were administered to DSS-induced colitis mice, evidenced by the amelioration in the colonic histological damage, which was associated with the downregulation in the production and release of pro-inflammatory cytokines (IL-6, IL-1β, IL-2 and TNF-α)." (PMID 36558455, 2022). "Despite the DSS-colitis is caused through the toxic damage of the intestinal and colonic epithelial cells, the inflammatory reactions ensue after the proinflammatory cytokines (Il-1β, Il-6, TNFα, and INFγ) production by tissue macrophages that seems to play an essential role in the disease process." (PMID 36384756, 2022). "Furthermore, they showed that silibinin could reduce the production of inflammatory cytokines and can protect against colitis-associated tumorigenesis in mice via inhibiting IL-6/STAT340." (PMID 36266431, 2022). "In addition, STAT3 is a critical IL-6 effector that induces colitis-associated colon cancer." (PMID 35372504, 2022). "Interestingly, steroid-resistant colitis is associated with high serum IL-6 concentrations." (PMID 33547295, 2021). "However, aberrant IL-6 responses are implicated in the pathogenesis of inflammatory diseases including Crohn’s disease and ulcerative colitis and blockade of IL-6 is protective in murine colitis." (PMID 32513301, 2020). "However, in IL-6 deficient mice treated with lipopolysaccharide or induced colitis, LRG1 increase can still be observed, suggesting there may be an IL-6 independent mechanism to upregulate LRG110." (PMID 32249825, 2020). "Moreover, recent findings demonstrated that cocoa suppresses the development of colitis-associated tumorigenesis by modulating NF-kB/IL-6/Signal transducer and activator of transcription 3 (STAT3) signaling pathways and also induces apoptosis by activating caspase-3 in a mouse model." (PMID 31031748, 2019). "Indeed, it was shown in the same study that deletion of STAT3 in the intestinal epithelium led to more severe DSS colitis with pronounced colonic ulcerations and body weight loss, indicating that the IL-6 response in the intestinal epithelial cells was important for regeneration." (PMID 31694340, 2019). "Maternal high-fat diet consumption enhances offspring susceptibility to dextran sulfate sodium-induced colitis in mice accompanied with upregulated NF-κB signaling, enhanced neutrophil infiltration, and elevated IL-6 levels, thereby further revealing TNFα and IL-6 as ideal targets for CRC therapies." (PMID 30591653, 2018). "Previous studies have shown that IL-6 and IL-10 play essential roles for the maintenance of intestinal homeostasis and the prevention of colitis, while proinflammatory cytokines, such as IL-17 and IL-15 promote intestinal dysbiosis associated with increased susceptibility to colitis." (PMID 28943876, 2017). "Moreover, administration of exogenous IL-23 in RAG mice reconstituted with naïve CD4+ T-cells caused a more severe colitis that was associated with enhanced production of IL-6 and IL-17 and preventable by treatment of mice with a blocking IL-6 or IL-17 antibody." (PMID 19503799, 2009). "The results showed that the concentrations of inflammatory factors in the colon tissue of colitis mice after oral gavage of A. actinomycetemcomitans were significantly higher than those in the DSS group (Il-6, P = 0.031; Il-1β, P = 0.005; Tnf-α, P < 0.0001)." (PMID 41531455, 2026). "Rag1−/− mice receiving CD4+ CD45Rbhi T cells alone developed severe colitis, as evidenced by increased weight loss, higher pathological scores, and intestinal TNF‐α and IL‐6 levels, which were inhibited by co‐transfer of WT or miR‐10a‐deficient Tregs." (PMID 41178490, 2026). "XXLP significantly improved colitis symptoms, including weight loss and colon shortening, and reduced the concentrations of inflammatory markers IL-1β, IL-18, TNF-α, and IL-6." (PMID 41901297, 2026). "DSS colitis resulted in elevated levels IL‐6, IL‐1a, TNF‐ɑ, and MCP‐1 in the colons of PBS control‐treated mice compared to naïve mice." (PMID 39815783, 2025).
colitis (continued). "Inflammation of the colonic mucosa is a key feature of colitis, where the role of pro-inflammatory mediators such as IL-1β, IL-6, IL-23 and TNF-α is well established." (PMID 40943092, 2025). "Research suggests that the active ingredient Renshen in WFC can effectively mitigate colitis by reducing cell infiltration and lowering levels of inflammatory markers such as IL-6 and TNF-α." (PMID 41284643, 2025). "Compared to the MOD group, varying doses of COP treatment significantly reduced the elevated serum levels of TNF-α, IFN-γ, and IL-6, thereby effectively preventing the development of colitis in mice." (PMID 40053041, 2025). "In DSS-induced colitis, UA lowered IL-6 levels and attenuated inflammatory cell infiltration, while in LPS-induced lung injury, it suppressed TNF-α, IL-1β, and IL-6 production while upregulating anti-inflammatory IL-10 expression." (PMID 40804950, 2025). "Disruption of IL‐6‐mediated STAT3 activation has been shown to attenuate colitis severity in animal models, highlighting the central role of IL‐6/STAT3 signaling in UC progression." (PMID 40387460, 2025). "IL-6 levels were significantly elevated in the vehicle-treated colitis group compared to the healthy control group (0.7 ± 0.1 vs. 87 ± 18; p < 0.0001)." (PMID 40869234, 2025). "In our experimental model of colitis, RvD2 treatment consistently led to a significant reduction in the expression of key pro-inflammatory cytokines, including TNFα and IL6, across all tested concentrations (0.01 μM, 0.1 μM, and 0.3 μM)." (PMID 40649782, 2025). "The colitis group demonstrated a significant increase in colon IL‐6 and STAT3 levels by 6.77‐fold (F = 505.4, p < 0.0001) and 4.38‐fold (F = 153.3, p < 0.0001), respectively, compared to the normal control group." (PMID 40387460, 2025). "In the colitis model, there is an increase in IL‐6 (interleukin‐6) expression, and the antibody to this protein has been demonstrated to exert an inhibitory effect on colitis." (PMID 39803293, 2025). "Glycyrrhiza chalcone inhibited TNF-α, IL-1β, and IL-6 expressions in the colon tissue of mice with colitis." (PMID 41180229, 2025). "TNF-α and IL-6 levels were significantly higher in Mcpt-4ΔCre colitis mice compared to control Mcpt-4ΔCre mice." (PMID 40697820, 2025). "Cow and human mEVs attenuated severity of colitis and reduced expression of Interleukin‐6 (IL‐6) and Tumor necrosis factor‐α." (PMID 40385535, 2025). "During progression of colitis, IL6/GP130/STAT3(Signal Transducer and Activator of Transcription 3) signaling pathway is upregulated in colonic epithelium, promoting development of colitis." (PMID 39821173, 2025). "The results of this study indicate that Pediococcus pentosaceus M6 can reduce the expression of IL-6 and IL-1β and increase the expression of IL-10, suggesting that Pediococcus pentosaceus M6 can effectively alleviate the progression of colitis in mice." (PMID 40431130, 2025). "The APS-H-treated colitis mice had down-regulated blood levels of IL-6, TNF-α, and IL-1β, whereas the DSS-treated mice had increased serum levels of these cytokines." (PMID 41010526, 2025). "DMS administration significantly alleviated colitis, as indicated by an increased colon length, reduced serum IL-6 levels, and improved histological scores." (PMID 40426955, 2025). "Reduced editing and Flna expression levels were associated with an increased expression of classical proinflammatory cytokines and chemokines like Il1b, Cxcl1, or Il6, which are typically induced during colitis." (PMID 40471139, 2025). "In both acute and chronic colitis models, vehicle-treated mice showed a significant increase in pro-inflammatory cytokines, IL-6, IL-1β, MCP-1, and TNF-α, compared to healthy controls, which was markedly attenuated by the combination therapies." (PMID 40869234, 2025).
colitis (continued). "Experimental studies reveal that mice with disrupted IL-6/gp130/STAT3 signaling develop more severe colitis, along with marked epithelial damage and ulceration upon AOM/DSS exposure, compared with wild-type counterparts." (PMID 40109347, 2025). "Heat-killed Companilactobacillus crustorum MN047 substantially reversed TNF-α and IL-6 in DSS induced colitis mice." (PMID 40219029, 2025). "In contrast to FOS, while 2′-FL and 3′-FL effectively mitigated barrier dysfunction caused by IL-6 and symptoms of DSS-induced colitis, they bolstered the expression of tight junction proteins (ZO-1 and Claudin-1) to enhance intestinal barrier function." (PMID 41464891, 2025). "The present study demonstrated that SS18‐50‐H treatment resulted in a reduction in mRNA expression of TNF‐α, COX‐2, IL‐10, and IL‐6 to levels within the normal range in colitis mice." (PMID 39803293, 2025). "Following SA-Q-CS treatment, IL-6 levels in colitis mice decreased by 66.7%, markedly reduced its congregation." (PMID 40842836, 2025). "Findings from this study indicate that DSS-induced colitis in rats leads to significantly increased levels of IL-1β, IL-6, TNF-α, and MDA, along with a notable decrease in SOD levels, suggesting severe oxidative damage and inflammatory responses." (PMID 40417008, 2025). "Studies on colitis have demonstrated that resting peritoneal macrophages from SUCNR1-deficient mice secrete less pro-inflammatory factors IL-1β, IL-6 and TNF-α and, thus, exert a protective effect against colitis." (PMID 40243444, 2025). "In the CSA cohort, vehicle-treated colitis mice exhibited marked elevations in IL-6 (p < 0.001), IL-1β (p < 0.0001), MCP-1 (p < 0.0001), and TNF-α (p < 0.0001) compared to healthy controls." (PMID 40869234, 2025). "Combining the STAT3 inhibitor JSI-124 with a strategy to inhibit IL-6-mediated production of the G-MDSC exosome miR-93-5p facilitates the prevention and treatment of colitis-associated cancer." (PMID 39990210, 2025). "To assess the effect of FBT on the inflammatory response in colitis mice, we used ELISA kits to detect the levels of inflammatory factors IL-1β, IL-6, and TNF-α in the serum." (PMID 40238292, 2025). "This was accompanied by a prominent increase in colonic mRNA of the proinflammatory cytokines Il‐1β, Tnfa, and Il‐6 as well as the interferon‐stimulated gene, Ifit2, in mice with colitis compared to the healthy controls." (PMID 40018982, 2025). "Modulating the Treg/Th2 response by decreasing proinflammatory cytokines such as TNFα, IL-6, IL-1β, IL-18, IL-22, IL-9 and increasing anti-inflammatory cytokines IL-10 and IL-4 in mice colitis model." (PMID 41208998, 2025). "Growing evidence indicates that during the onset of colitis, the body produces large amounts of pro-inflammatory cytokines (IL-6, TNF-α, IL-1β, etc.), primarily derived from macrophages and neutrophils." (PMID 41008172, 2025). "Meanwhile, ELISA analysis showed that 4-OI treatment significantly reduced levels of pro-inflammatory cytokines (IL-1β and IL-6) in both colitis tissues and serum." (PMID 41417165, 2025). "Pro-inflammatory cytokines, namely TNF-α, IL-1β, and IL-6, play pivotal roles in the inflammatory process, precipitating tissue damage and exacerbating colitis." (PMID 40077487, 2025). "Rev‐erb modulates the production of pro‐inflammatory cytokines including IL‐6 and regulates colitis via NF‐κB/Nlrp3 axis." (PMID 40911428, 2025). "The molecular mechanisms elucidated in this study suggest a multi-faceted approach, wherein Homo suppresses the expression of pro-inflammatory cytokines including, TNF-α, IL-1β, and IL-6, which are critical mediators in the pathogenesis of colitis." (PMID 40529132, 2025). "The IL-6/STAT3 signaling pathway is known to be involved in the pathogenesis of colitis and related cancers." (PMID 40295196, 2025).